GAS2 (growth arrest specific 2)
Description:
Required to maintain microtubule bundles in inner ear supporting cells, affording them with mechanical stiffness to transmit sound energy through the cochlea.
Synonyms: GAS-2; DFNB125
Tractability: Antibody: UniProt places it where antibodies can reach, with medium confidence; the Human Protein Atlas places it where antibodies can reach. PROTAC: ubiquitination databases record sites on it; its protein half-life has been measured.
Gene: Protein-coding gene on chromosome 11 (22,625,509 to 22,813,803, forward strand). Ensembl gene ENSG00000148935.
Subcellular location: Cytoplasm, cytoskeleton, stress fiber; Membrane
Subcellular location (Human Protein Atlas): Cytosol; Plasma membrane; Nucleoli; Nucleoplasm
Pathways (Reactome):
Programmed Cell Death: Caspase-mediated cleavage of cytoskeletal proteins
Gene Ontology:
Molecular function: actin filament binding; microtubule binding
Biological process: actin crosslink formation; apoptotic process
Cellular component: actin filament; cytosol; membrane; stress fiber
Genetic constraint (gnomAD): Loss-of-function variants: 16 observed, 32.17 expected, observed/expected ratio (o/e) 0.5, 90% interval 0.34 to 0.75. The upper end of that interval is the gene's LOEUF score, 0.75, which puts it in group 3 of 6, group 1 being the genes least tolerant of losing a copy. Missense variants: 304 observed, 357.96 expected, observed/expected ratio (o/e) 0.85, 90% interval 0.77 to 0.93. Synonymous variants: 130 observed, 128.52 expected, observed/expected ratio (o/e) 1.01, 90% interval 0.88 to 1.17.
Homologues: Orthologues: chimpanzee GAS2 (100% identical), macaque GAS2 (98% identical), dog GAS2 (98% identical), pig GAS2 (98% identical), mouse Gas2 (97% identical), guinea pig GAS2 (97% identical), tropical clawed frog gas2 (87% identical), rabbit GAS2 (76% identical), zebrafish gas2a (75% identical), rat Gas2 (22% identical). Paralogues in human: GAS2L1 (36% identical), ASPM (17% identical), MICALL2 (16% identical), MICALL1 (14% identical), EHBP1L1 (13% identical), EHBP1 (12% identical), SMTNL1 (4% identical).
Diseases named in the same sentence as GAS2 in open-access papers:
GAS2 is named in the same sentence as 39 diseases in open-access papers, as found by Europe PMC text mining. Sharing a sentence is not in itself a finding about the gene and the disease. The quoted sentences say what the papers report.
colorectal cancer (5 papers, 2014 to 2025). A primary or metastatic malignant neoplasm that affects the colon or rectum. "While mutations in GAS2 are infrequently reported in human cancers, elevated GAS2 expression has been documented in leukemia, colorectal cancer, among others 36-38." (PMID 39744572, 2025). "GAS2 expression is altered in different types of cancer, such as colorectal cancer 35, and it is important to note that this gene has been found to be overexpressed in CD34+ cells from CML patients." (PMID 29030909, 2017). "In colorectal cancer (CRC), fecal GAS2 was proposed as a non-invasive marker for early recurrence as it can be found in the feces of patients with recurrent CRC." (PMID 33333841, 2020). "Briefly, one cell proliferation marker, Ki-67 antigen (Ki-67), was upregulated in the cells with overexpressed GAS2, “Correlation between proliferation markers: PCNA, Ki-67, MCM-2 and antiapoptotic protein Bcl-2 in colorectal cancer”." (PMID 27284567, 2016). "On the contrary, the dominant negative form of GAS2 (GAS2DN) has the ability to release the inhibitory effect of both GAS2 and Calpastatin on calpain, and it inhibits the in vitro growth of HCT116 cells (colorectal cancer) by activating calpain to degrade beta-catenin." (PMID 24465953, 2014).
leukemia (5 papers, 2020 to 2025). A malignant (clonal) hematologic disorder, involving hematopoietic stem cells and characterized by the presence of primitive or atypical myeloid or lymphoid cells in the bone marrow and the blood. "Kaplan–Meier analysis indicated that GAS2 silencing significantly delayed leukemia generation, and western blot confirmed that GAS2 expression in leukemic cells (hCD45+GFP+) was lower from the GAS2 silenced group than that from the control group." (PMID 36054080, 2022). "In this study, a xenograft experiment was performed, which showed that GAS2 silencing delayed leukemia generation in immunodeficient mice." (PMID 36054080, 2022). "In such a scenario, GAS2, therefore, tends to be an oncogene of leukaemia, which is different from the suppressor role of GAS2 in HCC." (PMID 33103301, 2021). "Expression of the leukemia suppressor Irf8/Icsbp was decreased and Gas2 increased in GFP+Lin− vs. control Lin− cells, consistent with prior work." (PMID 32080344, 2020). "It is noteworthy that, in leukaemia cells, GAS2 also acts as an inhibitor of calpain activity." (PMID 33103301, 2021). "The potential roles of GAS2 protein in tumorigenesis of liver cancer, leukaemia, recurrent colorectal cancer, prostate cancer, breast cancer 44, 59 or lung adenocarcinoma 60 have been explored, but there are very few studies related to GAS2L1, GAS2L2 and GAS2L3." (PMID 33103301, 2021). "Notably, several essential genes involved in HSC self-renewal, metabolism, and leukemia development were increased, including GATA2, MSI2, MYCN, CD44, GAS2, HOXB4, and HOXB6." (PMID 38216972, 2024). "GAS2 is reportedly involved in the disease transformation of CML 52 and exhibits an opposite effect on the inhibition or emergency granulopoiesis termination roles of ICSBP for leukaemia." (PMID 33103301, 2021). "Interestingly, we observed the opposite effect of GAS2 protein on cell cycle, apoptosis and tumorigenesis issues between solid cancer (especially HCC) and leukaemia." (PMID 33103301, 2021).
chronic myeloid leukemia (3 papers, 2022 to 2025). "Conversely, in bone marrow progenitors with BCR-ABL+ (a fusion gene associated with chronic myeloid leukemia) or Icsbp-/-, high GAS2 expression stabilizes β-catenin, thereby promoting human leukemogenesis." (PMID 39744572, 2025).
hearing loss (3 papers, 2023 to 2025). "Our research significantly enhances the molecular diagnosis of hearing loss and lays the groundwork for future studies to develop new therapeutic strategies to prevent progressive hearing loss linked to GAS2." (PMID 40169809, 2025). "We identified a novel heterozygous mutation in GAS2 segregating with nonsyndromic hearing loss as a probable cause for hearing impairment in a dominant family (designated Family NT33)." (PMID 38956677, 2024). "By Whole-exome sequencing, we identified a novel heterozygous splicing variant in GAS2 (c.616–2 A > G) as the only candidate mutation segregating with late-onset and progressive nonsyndromic hearing loss (NSHL) in a large dominant family." (PMID 38956677, 2024). "Only a splicing variant (c.616–2 A > G in GAS2) segregating with hearing loss in the Family NT33 was identified." (PMID 38956677, 2024). "The findings provide a foundation for future investigations into new therapeutic strategies aimed at preventing progressive hearing loss associated with GAS2." (PMID 38956677, 2024). "Recently, it was reported that GAS2 protein harboring microtubule- and actin-binding domains was required to organize and stabilize the microtubules in PCs, and that GAS2-mutant mice showed a decrease in PC stiffness and hearing loss." (PMID 38069416, 2023). "As mutations leading to expression of C-terminally truncated GAS2 have been linked to hearing loss, these findings suggest that the disruption of GAS2-dependent cytoskeletal organisation could underlie auditory dysfunction." (PMID 40169809, 2025). "We assume that the affected members of this Chinese family exhibit lower GAS2 protein expression levels than healthy individuals, a characteristic that may indicate another pathological function of this novel GAS2 variant in hearing loss." (PMID 38956677, 2024). "This study expands the spectrum of GAS2 variants and elucidates the underlying pathogenic mechanisms, providing a foundation for future investigations of new therapeutic strategies to prevent GAS2-associated progressive hearing loss." (PMID 38956677, 2024). "However, the molecular mechanism through which GAS2 variant results in hearing loss remains unknown." (PMID 38956677, 2024). "Two GAS2 variants, c.616-2A > G (Chinese family in this study) and c.723 + 1G > A (Somalian family), locating at the 3’ splicing site and 5’ splicing site of the same exon respectively, both caused the C-terminal truncation of GAS2 protein and associated with the hearing loss." (PMID 38956677, 2024). "Given the previous report of another homozygous variant in GAS2 cosegregating with hearing loss in a family of Somalian descent, we speculated that the GAS2 c.616–2 A > G variant identified herein may be a cause of the progressive, late-onset hearing loss in Family NT33." (PMID 38956677, 2024). "Variants such as GAS2 c.723+1 G > A and GAS2 c.616–2 A > G introduce a stop codon within the GAR domain, resulting in disordered microtubule arrays, microtubule depolymerization, and inherited hearing loss." (PMID 40169809, 2025). "GAS2 colocalizes with these microtubule bundles, and the variants (GAS2 c.723+1G>A; GAS2 c.616–2A>G) introduce a stop codon within the GAR domain, resulting in disordered microtubule arrays and causing inherited hearing loss." (PMID 40169809, 2025).
hepatocellular carcinoma (3 papers, 2020 to 2025). A malignant tumor that arises from hepatocytes. "In contrast, GAS2 seems to act as a tumor suppressor by inhibiting cell growth in hepatocellular carcinoma." (PMID 33333841, 2020). "Similarly, upregulated GAS2 in a hepatocellular carcinoma (HCC) cell line (SK‐Hep1) suppresses the G1‐to‐S transition of the cell cycle." (PMID 33103301, 2021).
acute lymphoblastic leukemia (2 papers, 2022 to 2025). Leukemia with an acute onset, characterized by the presence of lymphoblasts in the bone marrow and the peripheral blood. "In contrast, GAS2/Calpain2 plays an oncogenic role in some other malignant cells partially through its regulation of β‐catenin, including T‐cell acute lymphoblastic leukemia (T‐ALL) cells." (PMID 36054080, 2022). "Growth arrest‐specific (GAS2) interacts with C‐X‐C motif chemokine receptor 4 (CXCR4) and enhances the stability of CXCR4 in T‐cell acute lymphoblastic leukemia (T‐ALL) cells, and the GAS2/CXCR4 axis activates the expression of NOTCH/c‐MYC and promotes T‐cell leukemogenesis." (PMID 36054080, 2022). "Although growth arrest‐specific protein 2 (GAS2) promotes the growth of T‐cell acute lymphoblastic leukemia (T‐ALL) cells in culture, the effect of GAS2 on T‐cell leukemogenesis has not been studied, and the mechanism remains unclear." (PMID 36054080, 2022).
cyst (2 papers, 2016 to 2021). A sac-like closed membranous structure that may be empty or contain fluid or amorphous material. "We have shown that GAS2 is mainly expressed in the somatic compartment of the ovary, either surrounding the perinatal oocyte cyst or surrounding postnatal growing follicles." (PMID 27734842, 2016). "Based on the role of the GAS2-like protein ortholog Pigs in the fly, we predicted a role for GAS2 in oocyte cyst breakdown and follicular assembly." (PMID 27734842, 2016). "Female Gas2 null mice are subfertile and exhibit disrupted oocyte cyst breakdown, a reduced number of large antral follicles and corpora lutea, and severely impaired organization of the basal lamina surrounding growing follicles." (PMID 27734842, 2016).
embryonal carcinoma (2 papers, 2021 to 2025). A non-seminomatous malignant germ cell tumor characterized by the presence of large germ cells with abundant cytoplasm resembling epithelial cells, geographic necrosis, high mitotic activity, and pseudoglandular and pseudopapillary structures formation. "Notably, the mRNA levels of Gas2 and other genes increased rapidly after retinoic acid treatment in the nutrient-deprived medium, indicating that Gas2 expression in mouse F9 embryonic carcinoma cells is influenced by varying nutritional conditions." (PMID 39744572, 2025). "For example, upon serum starvation, GAS2 protein was upregulated in the murine 3T3 cell line, and slightly upregulated in the F9 embryonal carcinoma cells, but not in the murine keratinocyte cell line MSCP5, suggesting the cell specificity of GAS2 function." (PMID 33103301, 2021). "For instance, Gas2 protein levels were found to increase upon serum starvation in the murine NIH 3T3 cell line 4, 30, and to a lesser extent in embryonal carcinoma F9 cells 21, but not in the murine keratinocyte MSCP5 cells, 31 suggesting the cell specificity of Gas2 function." (PMID 39744572, 2025).
glioma (2 papers, 2021 to 2025). A benign or malignant brain and spinal cord tumor that arises from glial cells (astrocytes, oligodendrocytes, ependymal cells). "Additionally, we only observed the potential association between the GAS2 gene expression and the prognosis of glioma cases in the seq_325 of the CGGA database." (PMID 33713047, 2021). "UCHL1 promotes lymphatic metastasis, distant metastasis, and worse prognosis in glioma patients by enhancing GAS2 expression." (PMID 41425852, 2025). "The aim of this study is thus to comprehensively analyze the potential functional links of the growth‐arrest‐specific 2 (GAS2) family genes with the pathogenesis or clinical prognosis of gliomas." (PMID 33713047, 2021). "We also analyzed the mutation status of GAS2, GAS2L1, GAS2L2, and GAS2L3 in the glioma samples of TCGA‐LGG/GBM or CGGA‐WEseq_286 project, respectively." (PMID 33713047, 2021). "Compared with GAS2, GAS2L1, and GAS2L2, there is a stronger correlation between GAS2L3 gene expression and glioma prognosis." (PMID 33713047, 2021). "In summary, compared with GAS2, GAS2L1, and GAS2L2, there is a stronger correlation between GAS2L3 gene expression and glioma prognosis." (PMID 33713047, 2021). "Herein, we first comprehensively explored the potential correlation between growth‐arrest‐specific two family genes (GAS2, GAS2L1, GAS2L2, GAS2L3) and gliomas by bioinformatics analysis and cellular experiments." (PMID 33713047, 2021). "Therefore, our findings did not provide strong evidence regarding the correlation between the expression of GAS2, GAS2L1, and GAS2L2 and the clinical prognosis of glioma cases." (PMID 33713047, 2021). "Apart from GAS2L3, we did not observe the strong evidence supporting the significant expression difference of the GAS2, GAS2L1, and GAS2L2 genes between glioma cases and negative controls." (PMID 33713047, 2021).
T-cell acute lymphoblastic leukemia (2 papers, 2021 to 2023). Acute lymphoblastic leukemia of T-cell origin. "The GAS2 protein is an apoptotic regulator that interacts with caspase-3 and caspase-7 and promotes the proliferation of T-cell acute lymphoblastic leukemia by activating the Wnt/β-catenin pathway." (PMID 36851380, 2023).
adenoma (1 paper, 2024). A neoplasm arising from the epithelium. "The comparative analysis of the transcriptional profiles of NAGs and ACAs revealed the overexpression of specific genes in all adenomas compared to normal adrenals, including IGF2R, GAS2 and SLBP." (PMID 39167619, 2024).
adrenocortical tumours (1 paper, 2024). "However, the function of both GAS2 and SLBP in adrenocortical tumours remains to be further investigated." (PMID 39167619, 2024).
breast carcinoma (1 paper, 2025). "Notably, the expression of GAS2 and other genes was low in breast cancer MCF-7 and HCC1954 cells." (PMID 39744572, 2025). "In a separate investigation, apoptosis induction in human breast cancer MCF-7 cells via UV treatment revealed that caspase-3, and caspase-7, recognize and cleave aspartic acid at position 279 of GAS2 during the early stages of apoptosis." (PMID 39744572, 2025).
Breast invasive carcinoma (1 paper, 2021). "For instance, compared with normal tissues of TCGA‐BRCA (Breast invasive carcinoma), we observed a lower expression level of GAS2 and GAS2L2 genes (p < 0.001), but a high expression level of GAS2L3 (p < 0.001) in the tumor tissues." (PMID 33713047, 2021).
female infertility (1 paper, 2022). Diminished or absent ability of a female to achieve conception. "However, previous reports have shown that Gas2 loss leads to female infertility by activating Notch signaling." (PMID 36054080, 2022).
Infertility (1 paper, 2016). "Loss of the GAS2 ortholog Pigs resulted in infertility in Drosophila24." (PMID 27734842, 2016).
liver cancer (1 paper, 2021). An epithelial or non-epithelial malignant neoplasm that arises from the liver. "Additionally, HBxΔ35 can downregulate the expression of GAS2 by binding to the promoter region of GAS2, thereby resulting in a reduced cell apoptosis level and facilitating the pathogenesis of liver cancer." (PMID 33103301, 2021).
myeloproliferative neoplasm (1 paper, 2022). A clonal hematopoietic stem cell disorder, characterized by proliferation in the bone marrow of one or more of the myeloid (i.e., granulocytic, erythroid, megakaryocytic, and mast cell) lineages. "In addition, GAS2 silencing did not disturb the growth of normal CD3+ or CD34+ cells, which supports GAS2 as a suitable therapeutic target to eradicate T‐ALL cells or other hematological malignancies with aberrant GAS2 expression, such as CML and myeloproliferative neoplasm." (PMID 36054080, 2022).
sterility (1 paper, 2024). "Studies in Drosophila, pigs and mice have shown that GAS2 mutation results in sterility." (PMID 38937400, 2024).